FBXO22 (F-box protein 22)
Diseases named in the same sentence as FBXO22 in open-access papers (continued):
Sharing a sentence is not in itself a finding about the gene and the disease.
lung carcinoma (continued). "To reveal the clinical significance of FBXO22 in lung cancer, we examined the expression levels of FBXO22 in lung cancer cells and lung cancer tissues and analyzed the correlation between FBXO22 expression and the patients’ prognosis according to their survival information." (PMID 38296976, 2024). "In the present study, we found that FBXO22 was aberrantly highly expressed in lung cancer and could serve as a novel molecular biomarker of radioresistance." (PMID 38296976, 2024). "FBXO22 silencing increased the radiosensitivity of lung cancer cells." (PMID 38296976, 2024). "Additionally, immunohistochemical (IHC) staining of paired tissue samples collected from our lung adenocarcinoma patients also indicated that the expression of FBXO22 was dramatically elevated in lung cancer tissues." (PMID 38296976, 2024). "Thus, FBXO22 is likely to activate HR through the upregulation of Rad51, thereby leading to lung cancer radioresistance." (PMID 38296976, 2024). "Given that FBXO22 mediates the hemin-induced degradation of BACH1 in lung cancer cells, we assessed whether FBXO22 facilitates BACH1 degradation in MLLr AML cells." (PMID 36774506, 2023). "Similarly, FBXO22 promoted lung cancer cell growth through the LKB1/AMPK/mTOR signaling pathway, but inhibited metastasis by suppressing Bach1." (PMID 36127346, 2022). "In addition, recent evidence suggests that in mouse models of lung cancers, activated Nrf2 inhibits the Fbxo22-dependent degradation of Bach1 via induction of Ho-1 expression, and high levels of Bach1 promoting metastasis." (PMID 32576270, 2020). "We thus investigated whether FBXO22-mediated inhibition of LKB1 activity regulates lung cancer cell proliferation." (PMID 31217475, 2019). "The results showed that the phosphorylation of AMPKα was induced in FBXO22 knockout MEF cells, and knockdown of FBXO22 increased while induced FBXO22 expression decreased AMPK phosphorylation in LKB1-proficient lung cancer cells, suggesting FBXO22 is critical for maintaining LKB1 activity." (PMID 31217475, 2019). "Moreover, an increase of FBXO22 protein level in tumor tissues over adjacent normal tissues was also confirmed by western blot analysis in six paired clinical lung cancer specimens." (PMID 31217475, 2019). "Our transcriptome sequencing results showed that differentially expressed genes produced by FBXO22 silencing were significantly enriched in the HR pathway, indicating that overexpression of FBXO22 in lung cancer may induce radioresistance by activating the HR pathway." (PMID 38296976, 2024). "Therefore, we propose that FBXO22 controls the cell cycle by regulating substrate protein levels, which we confirmed in the lung cancer cell line A549: overexpression of FBXO22 increased the expression of cyclin-dependent kinase 4 (CDK4) and promoted cell proliferation." (PMID 35141150, 2021). "Intriguingly, the ectopically expressed FBXO22 did not cause apparent change in cell proliferation in LKB1-deficient lung cancer cells, but could dramatically rescue LKB1-mediate cell growth inhibition in LKB1 expressed lung cancer cells." (PMID 31217475, 2019). "BACH1 stability is sensitive to heme or hemin, which are essential for E3 ubiquitin ligases, including HOIL-1 and FBXO22, mediated BACH1 degradation via proteasome in lung cancer cells." (PMID 40263598, 2025). "In summary, FBXO22 increases the expression of Rad51 in a FOXM1-dependent manner, which in turn triggers lung cancer radioresistance." (PMID 38296976, 2024). "Mechanistically, FBXO22 promoted Rad51 gene transcription by increasing the level of FOXM1 at the Rad51 promoter, thereby inducing the formation of lung cancer radioresistance." (PMID 38296976, 2024). "FBXO22 increases the cisplatin sensitivity of tumour cells by mediating the ubiquitination and degradation of CD147 in A549 lung cancer cells." (PMID 39153212, 2024).
lung carcinoma (continued). "Mechanistically, FBXO22 promoted Rad51 gene transcription by increasing the level of FOXM1 at the Rad51 promoter, which contributes to insensitivity to lung cancer radiotherapy." (PMID 38296976, 2024). "Collectively, FBXO22 increases the level of FOXM1 at the Rad51 promoter, which in turn enhances the transcriptional activity of Rad51 and ultimately leads to lung cancer radioresistance." (PMID 38296976, 2024). "To define the effect of deguelin on the inhibition of FBXO22, we first measured its IC50 value in two lung cancer cell lines and selected 50 μM accordingly for subsequent experiments." (PMID 38296976, 2024). "On the contrary, FBXO22 facilitated tumorigenesis and progression via regulating the ubiquitination and degradation of p21 in hepatocellular carcinoma, of LKB1 in lung cancer, and of nuclear PTEN in colorectal cancer." (PMID 35046938, 2021). "For this purpose, LKB1 and FBXO22 were separately transfected or cotransfected into LKB1 null A549 and H460 lung cancer cells, and cell growth of these cells was measured by cell counting and colony formation assay." (PMID 31217475, 2019). "Although FBXO22 was proposed as a specific ubiquitin E3 for SCF-mediated BACH1 degradation in lung cancer cells, experimental evidence for FBXO22-mediated BACH1 ubiquitination in vitro have not yet been obtained." (PMID 40263598, 2025). "As expected, the expression of FBXO22 was generally upregulated in lung cancer cell lines (A549, H1299, H460, and H1975) compared with normal human bronchial epithelial BEAS-2B cells." (PMID 38296976, 2024). "Mechanistically, FBXO22 facilitated transcriptional activation of the homologous recombinase Rad51 through upregulation of the transcription factor FOXM1, thus promoting DNA damage repair and lung cancer radioresistance." (PMID 38296976, 2024). "Similarly, nuclear factor erythroid‐related factor 2 accelerated tumour metastasis via the suppression of FBXO22‐mediated degradation of BTB domain and CNC homologue 1 in lung cancer." (PMID 39153212, 2024). "Therefore, we conclude that FBXO22 upregulates the expression of FOXM1 and FOXM1 directly binds to the Rad51 promoter to transactivate Rad51, which ultimately leads to lung cancer radioresistance." (PMID 38296976, 2024). "For example, increased expression of FBXO22 has been shown in HCC, melanoma, and lung cancer." (PMID 36127346, 2022). "High expression of FBXO22 is correlated with worse prognosis in HCC and lung cancer." (PMID 36127346, 2022). "In addition, FBXO22 was shown to mediate BTB domain and CNC homolog 1 (BACH1) degradation, inhibiting migration in lung cancer cells." (PMID 35141150, 2021). "FBXO22 could ubiquitinate CD147 and result in its degradation, leading to enhancement of cisplatin sensitivity in lung cancer cells." (PMID 32793396, 2020). "Here, we show that FBXO22 is highly expressed in lung cancer using information not only from available database but also from clinical tumor tissues." (PMID 31217475, 2019). "The TCGA dataset analysis showed that the negative correlation between FBXO22 expression and OS could not be found in patients with mutation or deletion LKB1 expression, suggesting the potential link of FBXO22 and LKB1 in lung cancer." (PMID 31217475, 2019). "Identification of the FBXO22/LKB1/AMPK/ mTOR axis in this study not only provides great insight into how LKB1 kinase activity is regulated, but also highlights FBXO22 as a potential target for lung cancer therapy." (PMID 31217475, 2019). "However, when we used the GEPIA2 tool to perform survival analysis in the lung cancer datasets LUAD and LUSC from the TCGA, we discovered no such correlations between FBXO22 expression and OS." (PMID 35141150, 2021).
hepatocellular carcinoma (11 papers, 2015 to 2024). A malignant tumor that arises from hepatocytes. "Another F-box protein, FBXO22, is increased in hepatocellular carcinoma or cervical carcinoma, where it promotes cancer progression by binding to p57KIP2 and targeting it to degradation, similar to Fbxo22-mediated p21CIP degradation." (PMID 38561743, 2024). "FBXO22 promotes hepatocellular carcinoma by regulating p21 ubiquitination and degradation." (PMID 37348029, 2023). "FBXO22 increased hepatocellular carcinoma progression via targeting KLF4 and p21 for degradation." (PMID 36127346, 2022). "One study revealed that FBXO22 facilitates hepatocellular carcinoma (HCC) progression by regulating Kruppel‐like transcription factor 4 for destabilization." (PMID 39153212, 2024). "In addition, FBXO22 has been discussed as a new potential therapeutic target for hepatocellular carcinoma; based on our analysis, FBXO22 may be a valuable drug target for multiple cancer therapies." (PMID 35141150, 2021).
renal cell carcinoma (7 papers, 2019 to 2024). "For example, FBXO22 reduces tumour metastasis via the suppression of matrix metalloproteinase‐9 (MMP‐9)‐involved invasion and migration and the blockade of VEGF‐induced angiogenesis in renal cell carcinoma." (PMID 39153212, 2024).
lung adenocarcinoma (6 papers, 2019 to 2024). A carcinoma that arises from the lung and is characterized by the presence of malignant glandular epithelial cells. "Additionally, we found that FBXO22 mutations were accompanied by altered substrate expression, especially in uterine corpus endometrial carcinoma and lung adenocarcinoma; endometrial carcinoma patients with FBXO22 genetic alterations also had better overall and relapse-free survival." (PMID 35141150, 2021). "Multiple algorithms revealed that high FBXO22 expression was associated with lower TIL levels, especially in lung adenocarcinoma, lung squamous cell carcinoma, and sarcoma." (PMID 35141150, 2021). "Overexpression of FBXO22 has been reported to suppress the Bach1‐driven metastasis of lung adenocarcinoma and promote nuclear tumor suppressive factor PTEN downregulation to play a tumor-promoting role in colorectal cancer." (PMID 33622332, 2021). "Next, we performed IHC staining on 84 lung adenocarcinoma tissues and the matched adjacent normal tissues, and found that lung adenocarcinoma tissues presented higher FBXO22 expression compared with adjacent normal tissues." (PMID 31217475, 2019). "Clinically, FBXO22 is highly expressed in human lung adenocarcinoma and high FBXO22 expression predicts significant poor prognosis." (PMID 31217475, 2019). "Moreover, IHC staining result indicated that higher expresson of FBXO22 existed in lung adenocarcinoma tissues than adjacent normal tissues." (PMID 32793396, 2020). "Moreover, FBXO22 is highly expressed in lung adenocarcinoma patients, and promotes NSCLC cell growth via inhibiting LKB1/AMPK/mTOR signaling." (PMID 31217475, 2019). "In addition, FBXO22 is highly expressed in human lung adenocarcinoma and high FBXO22 expression predicts significant poor prognosis." (PMID 31217475, 2019).
melanoma (6 papers, 2020 to 2025). A malignant, usually aggressive tumor composed of atypical, neoplastic melanocytes. "In malignant melanoma, FBXO22 increases tumor cell invasiveness and angiogenesis through the HIF-1α and VEGF pathways." (PMID 40534867, 2025). "The authors showed a higher expression of FBXO22 in metastatic melanomas compared to normal skin tissue." (PMID 33800394, 2021). "FBXO22 downregulation in melanoma cells suppressed migration, invasion and angiogenesis, and decreased the formation of blood vessels in nude mice." (PMID 32793396, 2020). "Importantly, knockdown of FBXO22 has been shown to inhibit tumor progression and metastasis in vivo, highlighting its potential as a therapeutic target for melanoma treatment." (PMID 40534867, 2025). "For instance, FBXO22 promotes melanoma progression and metastasis by upregulating HIF-1α and VEGF." (PMID 38296976, 2024). "Moreover, FBXO22 promoted the motility of melanoma cells and angiogenesis through upregulation of HIF1α and VEGFA49." (PMID 32793396, 2020). "FBXO22, a substrate receptor of the SCF ubiquitin ligases, has been reported to play a promoting role in melanoma, liver cancer, cervical cancer, and other cancers." (PMID 38519492, 2024). "Knockdown of FBXO22 attenuated cell migration, invasion, and angiogenesis via regulation of the HIF-1α/VEGF pathway in melanoma." (PMID 36127346, 2022). "Moreover, the downregulation of FBXO22 did not impair melanoma cell proliferation in vitro, but affected their migration in vitro and in vivo." (PMID 33800394, 2021).
cervical carcinoma (5 papers, 2022 to 2025). A carcinoma arising from either the exocervical squamous epithelium or the endocervical glandular epithelium. "Therefore, we carried out the current study to investigate biological functions of FBXO22 in cervical cancer and its underlying regulatory mechanism." (PMID 36127346, 2022). "In cervical cancer cells, ectopic expression of FBXO22 promotes the viability of cervical cancer cells in vitro and facilitates tumour growth in vivo." (PMID 39153212, 2024). "Ectopic expression of FBXO22 attenuates cell apoptosis and facilitates G1/S phase progression in cervical cancer cells." (PMID 39153212, 2024). "Our study provides an experimental basis for targeting FBXO22 as a potential strategy for cervical cancer intervention." (PMID 36127346, 2022). "Moreover, a CC tissue microarray, containing 116 cervical carcinomas and 31 adjacent cervical epithelial tissues, was performed to evaluate the difference of FBXO22 protein expression by IHC staining assay." (PMID 36127346, 2022). "Interestingly, our migration and invasion data showed that overexpression of FBXO22 inhibited cell migratory and invasive abilities in cervical cancer." (PMID 36127346, 2022). "In HPV-positive cervical cancer, ELK4 promotes cell cycle progression and stemness by modulating the FBXO22/PTEN axis." (PMID 41502523, 2025). "The expression of FBXO22 and p57Kip2 proteins in 10 paired cervical cancer tissues and adjacent non-tumor tissues were analyzed by Western blotting." (PMID 36127346, 2022).
non-small cell lung carcinoma (5 papers, 2020 to 2024). A group of at least three distinct histological types of lung cancer, including non-small cell squamous cell carcinoma, adenocarcinoma, and large cell carcinoma. "In non-small cell lung cancer, FBXO22 promotes Lys63-linked polyubiquitination of liver kinase B1 (LKB1), reducing its activity and impeding the LKB1-AMPK-mTOR pathway, thereby enhancing cell proliferation." (PMID 39048965, 2024). "For example, FBXO22 can activate PD-L1 ubiquitination and degradation, thereby increasing the sensitivity of non-small cell lung cancer cells to DNA damage therapies." (PMID 37340423, 2023). "LKB1 expression level is regulated by FBXO22 via proteasome-mediated degradation in non-small cell lung cancer (NSCLC) cells." (PMID 32793396, 2020). "One experiment showed that FBXO22 could activate the ubiquitination of PD-L1 to increase the sensitivity of non-small cell lung cancer cells to DNA damage, with CDK5 acting as an upstream regulator of FBXO22." (PMID 39048965, 2024). "FBXO22 overexpression elevated cell growth in non-small cell lung cancer (NSCLC)." (PMID 36127346, 2022).
colon cancer (4 papers, 2019 to 2024). "Collectively, our findings indicate that overexpression of FBXO22 contributes to downregulation of nuclear PTEN in colon cancer tissues." (PMID 32249768, 2020). "For example, FBXO22 selectively ubiquitinates PTEN in the nucleus to accelerate its degradation by the proteasome and promote the occurrence of colon cancer." (PMID 38519492, 2024).
colorectal cancer (4 papers, 2020 to 2022). A primary or metastatic malignant neoplasm that affects the colon or rectum. "Herein we report that FBXO22 ubiquitylates and targets nuclear but not cytoplasmic PTEN for proteasome-mediated degradation, through which FBXO22 contributes to nuclear PTEN downregulation in colorectal cancer and exerts tumorigenic function." (PMID 32249768, 2020). "Consistently, FBXO22 was also reported to enhance colorectal cancer development." (PMID 36127346, 2022). "In addition, upregulation of FBXO22 mRNA was confirmed by quantitative real-time PCR (qRT-PCR) in cancer tissues of a cohort of 37 colorectal cancer patients compared to adjacent normal tissues." (PMID 32249768, 2020). "In accordance, FBXO22 is overexpressed in various cancer types, and contributes to nuclear PTEN downregulation in colorectal cancer tissues." (PMID 32249768, 2020). "To investigate the influence of upregulated cancerous FBXO22 on nuclear PTEN in tumor tissues, we also performed immunohistochemistry (IHC) staining with the tissue microarray of human colorectal cancer tissues and paired normal tissues (n = 72)." (PMID 32249768, 2020). "Moreover, we confirmed that the absence of nuclear PTEN was more prominent than cytoplasmic PTEN in the cancer tissues of colorectal cancer patients, and this absence of nuclear PTEN was correlated with the overexpression of FBXO22 in cancer tissues." (PMID 32249768, 2020).
gastric cancer (3 papers, 2020 to 2024). A primary or metastatic malignant neoplasm involving the stomach. "He and colleagues have reported that circ_0006282 sponges miR‐155 and elevates FBXO22 expression, contributing to gastric cancer progression." (PMID 39153212, 2024).